MT1G (metallothionein 1G)
Description:
Metallothioneins have a high content of cysteine residues that bind various heavy metals; these proteins are transcriptionally regulated by both heavy metals and glucocorticoids.
Synonyms: MT1K; MT1
Tractability: PROTAC: ubiquitination databases record sites on it.
Gene: Protein-coding gene on chromosome 16 (56,666,730 to 56,668,069, reverse strand). Ensembl gene ENSG00000125144.
Pathways (Reactome):
Cellular responses to stimuli: Metallothioneins bind metals
Gene Ontology:
Molecular function: protein binding; zinc ion binding; metal ion binding
Biological process: cellular response to cadmium ion; cellular response to copper ion; cellular response to vascular endothelial growth factor stimulus; cellular response to zinc ion; negative regulation of growth; detoxification of copper ion; intracellular zinc ion homeostasis; monocyte activation; monocyte differentiation
Cellular component: cytoplasm; nucleus
Genetic constraint (gnomAD): Loss-of-function variants: 9 observed, 10.16 expected, observed/expected ratio (o/e) 0.89, 90% interval 0.53 to 1.53. The upper end of that interval is the gene's LOEUF score, 1.53, which puts it in group 6 of 6, group 1 being the genes least tolerant of losing a copy. Missense variants: 79 observed, 79.93 expected, observed/expected ratio (o/e) 0.99, 90% interval 0.82 to 1.19. Synonymous variants: 31 observed, 29.42 expected, observed/expected ratio (o/e) 1.05, 90% interval 0.79 to 1.42.
Homologues: Orthologues: zebrafish mt2 (61% identical). Paralogues in human: MT2A (94% identical), MT1F (92% identical), MT1A (89% identical), MT1H (89% identical), MT1HL1 (87% identical), MT1X (85% identical), MT1B (84% identical), MT1M (81% identical), MT3 (71% identical), MT4 (61% identical), MT1E (53% identical).
Diseases named in the same sentence as MT1G in open-access papers:
MT1G is named in the same sentence as 61 diseases in open-access papers, as found by Europe PMC text mining. Sharing a sentence is not in itself a finding about the gene and the disease. The quoted sentences say what the papers report.
hepatocellular carcinoma (33 papers, 2012 to 2024). A malignant tumor that arises from hepatocytes. "In addition, combined MT1M and MT1G promoter methylation in hepatocellular carcinoma patients was associated with a high incidence of vascular invasion and lymph node or extrahepatic metastasis, thereby acting as an effective prognostic marker." (PMID 30139373, 2018). "In a pilot study involving patients with hepatocellular carcinoma treated with sorafenib, MT1G has been identified as a biomarker for predicting the development of resistance to sorafenib treatment." (PMID 38844964, 2024). "MT1G inhibited the proliferation, migration, and invasion of hepatocellular carcinoma cells in both in vivo and in vitro experiments." (PMID 39061894, 2024). "Nevertheless, inhibiting the expression of MT-1G will enhance the metastatic tumor activity of sorafenib against hepatoma." (PMID 35354376, 2022). "Upregulation of MT-1G expression results in a reduction in ferroptosis, which in turn protects hepatocellular carcinoma cells from the action of sorafenib and contributes to the progression of cancer." (PMID 35993016, 2022). "MT1G hypermethylation occurs in a variety of tumors, including hepatocellular carcinoma, colorectal cancer, prostate cancer and gastric cancer." (PMID 35167648, 2022). "Metallothionein-1G (MT1G) negatively regulates ferroptosis in human hepatocellular carcinoma (HCC) cells." (PMID 35847022, 2022). "Upregulation of MT-1G expression protects hepatocellular carcinoma cells from the effect of sorafenib and promotes cancer progression by inhibiting ferroptosis." (PMID 34775496, 2021). "Meanwhile, metallothionein-1G silencing (MT-1G) was reported to enhance the sensitivity of hepatoma cells to sorafenib by triggering ferroptosis." (PMID 33931597, 2021). "Previous studies have linked the down-regulation of MT1F, MT1G, and MT1H to hepatocellular carcinoma, and the down-regulation HOXA to breast cancer with the whole cluster silenced." (PMID 32841292, 2020). "For example, in the treatment of advanced hepatocellular carcinoma, sorafenib resistance has been shown to result from the metallothionein-1G-induced inhibition of ferroptosis." (PMID 30737476, 2019). "Specifically, they showed that enhanced MT1G expression contributed to sorafenib resistance in hepatocellular carcinoma by inhibiting lipid peroxidation-mediated ferroptosis." (PMID 30139373, 2018). "The microarray studies identified MT-1G gene expression as downregulated in PTC and FTC, supporting recent reports of MT-1G suppressor role in human colon and hepatocellular carcinoma." (PMID 23273222, 2012). "MT1G was previously reported to inhibit ferroptosis by blocking glutathione depletion-mediated lipid peroxidation in hepatocellular carcinoma cells and clear cell renal cell carcinoma, and to promote sorafenib resistance in hepatocellular carcinoma cells." (PMID 39359721, 2024). "The expression of MT1G in hepatocellular carcinoma (HCC) was similar to that in ccRCC." (PMID 36204178, 2022). "MT1G as a critical regulator of sorafenib resistance could inhibit sorafenib-induced ferroptosis in hepatocellular carcinoma through decreased glutathione depletion and lipid peroxidation." (PMID 36386203, 2022). "In addition, MT1G down-regulated expression in prostate cancer and hepatocellular carcinoma resulted from hypermethylation of its promoter." (PMID 35167648, 2022). "In previous studies, MT1G suppression was reported to contribute to carcinogenesis in papillary thyroid carcinoma, prostate cancer, esophageal squamous cell carcinoma, hepatocellular carcinoma, and hepatoblastoma, and the mechanism of MT1G gene silencing was related to promoter hypermethylation." (PMID 30139373, 2018). "Metallothionein 1G (MT1G), an Nrf2 target gene, helps hepatocellular carcinoma (HCC) cells resist ferroptosis." (PMID 39737174, 2024).
hepatocellular carcinoma (continued). "MT1G belongs to the metallothionein superfamily and can be highly inducible in response to stress factors, including metal ions, and MT1G has been reported to inhibit lipid peroxidation mediated ferroptosis, protect cells from sorafenib injury and promote tumor growth in hepatocellular carcinoma." (PMID 35360452, 2021). "For instance, Metallothionein-1G (MT-1G) facilitates sorafenib resistance in hepatocellular carcinoma (HCC) cells, while knockdown of MT-1G can deplete glutathione and induce ferroptosis in sorafenib-treated HCC cells, thus restoring sensitivity of HCC cells to sorafenib." (PMID 38700533, 2024). "Although the expression of MT1G in breast, thyroid cancer, and hepatocellular carcinoma was downregulated compared to that in non-cancerous tissue, it has been reported that the expression of MT1G in NSCLC is higher than that in non-malignant lung tissues." (PMID 35354498, 2022).
thyroid cancer (8 papers, 2013 to 2024). "Over the past few years, it has been reported that MT1G deficiency promotes thyroid cancer cells proliferation and metastasis." (PMID 35167648, 2022). "However, the molecular mechanisms underlying MT1G as a tumor suppressor in thyroid cancer remain totally unknown." (PMID 24098937, 2013). "Previous study demonstrated that MT1G functions as a tumor suppressor in thyroid cancer thus suppressing cell proliferation in thyroid cancer cells." (PMID 35167648, 2022). "In thyroid cancer, the restoration of MT1G expression can inhibit the proliferation of thyroid cancer cells in vivo and in vitro, suggesting that it has a tumor suppressor effect." (PMID 35167648, 2022). "Further studies have found that MT1G inhibits thyroid cancer cells by inhibiting the proliferation and migration through the PI3K/AKT pathway." (PMID 35167648, 2022). "MT1G (metallothionein 1G) expression was frequently silenced or downregulated in thyroid cancer cell lines and was also significantly decreased in primary thyroid cancer tissues compared with non-malignant thyroid tissues." (PMID 28923001, 2017). "The aim of this study is to examine the biological functions and related molecular mechanisms of MT1G in thyroid cancer." (PMID 24098937, 2013). "In summary, our data showed that MT1G acted as a tumor suppressor, which was frequently inactivated by epigenetic alterations, such as promoter methylation and histone modification, in thyroid cancer." (PMID 24098937, 2013). "Taken together, MT1G exhibits the growth inhibitory ability in thyroid cancer cells and acts as a potential tumor suppressor." (PMID 24098937, 2013). "MT1G hypermathylation was found in 30.2% (64/212) of thyroid cancers, including 31.5% (56/178) of PTC, 25.0% (4/16) of FTC, 22.2% (2/9) of MTC, and 22.2% (2/9) of ATC." (PMID 24098937, 2013). "Collectively, MT1G inhibits thyroid cancer cell growth mainly through regulating PI3K/Akt signaling pathway." (PMID 24098937, 2013). "Delightedly, our data showed that MT1G restoration increased E-cadherin expression, resulting in the inhibition of migration and invasion in thyroid cancer cells." (PMID 24098937, 2013). "To better understand the tumor suppressive effect of MT1G in thyroid tumorigenesis, we investigated the effect of MT1G on the activities of two major signaling pathways in thyroid cancer, including the PI3K/Akt and MAPK pathways." (PMID 24098937, 2013). "Although the evidence has highlighted the importance of MT1G as an oncosuppressor in thyroid cancer, the precise molecular mechanisms remain largely unclear." (PMID 24098937, 2013). "MT1G restoration in thyroid cancer cells showed significant growth-suppressing effect by inhibiting cell proliferation and colony formation in the present study." (PMID 24098937, 2013). "Of note, MT1G hypermethylation significantly increased the risk of lymph node metastasis in PTC patients, as supported by our findings that MT1G restoration dramatically inhibited the migration and invasion of thyroid cancer cells." (PMID 24098937, 2013). "MT1G expression was frequently silenced or down-regulated in thyroid cancer cell lines, and was also significantly decreased in primary thyroid cancer tissues compared with non-malignant thyroid tissues." (PMID 24098937, 2013). "Because frequent MT1G hypermethylation was demonstrated in thyroid cancers, particularly in PTC, the association of MT1G hypermethylation with clinicopathological characteristics was analyzed in a total of 178 PTC." (PMID 24098937, 2013). "Previous studies showed that MT1G expression was repressed by promoter methylation in several human cancers, including hepatocellular cancer, colorectal cancer, prostate cancer and thyroid cancer." (PMID 24098937, 2013). "MT1G expression was silenced or down-regulated in all thyroid cancer cell lines compared with normal thyroid epithelial cell line HTori3." (PMID 24098937, 2013).
thyroid cancer (continued). "MT1G expression is frequently silenced or downregulated in thyroid cancer cell lines." (PMID 38068944, 2023). "Furthermore, previous study reported that MT1G acted as a tumor suppressor in thyroid cancer through regulating the PI3K/AKT signaling pathway." (PMID 35167648, 2022). "Thus, we next attempted to explore the effect of MT1G restoration on the migration and invasion of thyroid cancer cells." (PMID 24098937, 2013). "We thus tested the putative tumor suppressor function of MT1G in human thyroid cancer cells." (PMID 24098937, 2013). "To determine whether MT1G expression is regulated by epigenetic mechanisms in thyroid cancer, such as promoter methylation and histone modification, we examined MT1G expression in 6 thyroid cancer cell lines by conventional RT-PCR." (PMID 24098937, 2013). "Our data showed that SAHA dramatically induced MT1G expression in thyroid cancer cells, suggesting that histone deacetylation may be another crucial mechanism of MT1G inactivation in thyroid cancer." (PMID 24098937, 2013). "Thus, we supposed that other epigenetic mechanisms, such as histone modification, along with DNA methylation, were involved in MT1G inactivation in thyroid cancer cells." (PMID 24098937, 2013). "MT1G inactivation mediated by promoter methylation has been reported in thyroid cancer." (PMID 24098937, 2013). "Importantly, our data for the first time revealed that ectopic expression of MT1G in thyroid cancer cells dramatically inhibited cell growth and invasiveness, and induced cell cycle arrest and apoptosis via modulating the activity of PI3K/Akt pathway." (PMID 24098937, 2013). "Moreover, restoration of MT1G expression in thyroid cancer cells inhibited cell growth in vitro and in vivo, suggesting an oncosuppressor role." (PMID 24098937, 2013). "Importantly, restoring MT1G expression in thyroid cancer cells dramatically suppressed cell growth and invasiveness, and induced cell cycle arrest and apoptosis through inhibiting phosphorylation of Akt and Rb." (PMID 24098937, 2013). "The reduced expression of MT1G is closely associated with promoter methylation, as confirmed by MSP assays and pharmacological DNA demethylation treatment in the present study and a previous study, implicating DNA methylation as a regulatory mechanism of MT1G inactivation in thyroid cancer." (PMID 24098937, 2013). "Frequent down-regulation or silencing of MT1G mediated by epigenetic alterations in thyroid cancer cell lines and primary thyroid cancers but not in non-malignant thyroid tissues implicated that MT1G may be a tumor suppressor." (PMID 24098937, 2013). "In thyroid cancer, compared to malignant cells of the primary tumor, the characteristic of lymph node metastatic cells is the upregulation of MT1X and MT1G." (PMID 38747739, 2024). "Thus, we supposed that MT1G may play a role in the migration and invasion of thyroid cancer cells." (PMID 24098937, 2013). "In support of this, we treated thyroid cancer cells with a histone deacetylase inhibitor, SAHA, alone or in combination with 5-Aza-dC to explore the role of histone deacetylation in regulating MT1G expression." (PMID 24098937, 2013). "In the present study, we found that MT1G expression was frequently absent or down-regulated in thyroid cancer cell lines, and was also significantly decreased in primary thyroid cancer tissues compared with non-malignant thyroid tissues, which was consistent with the previous studies." (PMID 24098937, 2013). "Our data showed that ectopic expression of MT1G strongly inhibited phosphorylation of Akt, but not Erk1/2, in thyroid cancer cells, suggesting that MT1G may play its tumor suppressor role through modulating the activity of PI3K/Akt pathway." (PMID 24098937, 2013).
thyroid cancer (continued). "To gain insights into the downstream signaling pathways modulated by MT1G in tumor inhibition, we investigated the effect of MT1G on the activities of PI3K/Akt and MAPK pathways, which play a key role in cell proliferation and survival in human cancers, including thyroid cancer." (PMID 24098937, 2013).
liver cancer (7 papers, 2017 to 2025). An epithelial or non-epithelial malignant neoplasm that arises from the liver. "The activation of the Nrf2 pathway in liver cancer cells can upregulate the expression of metallothionein-1G (MT-1G) and promotes sorafenib drug resistance by inhibiting ferroptosis." (PMID 36160450, 2022). "Sorafenib can induce the expression of metallothionein-1G (MT-1G) gene in liver cancer cells, thereby inhibiting ferroptosis and promoting drug resistance." (PMID 34413966, 2021). "Other examples from the p62–Keap1–NRF2 pathway and metallothionein-1G (MT-1G) suggest that ferroptosis is strictly inhibited in liver cancer cells." (PMID 33372599, 2020).
prostate carcinoma (7 papers, 2018 to 2024). A carcinoma that arises from epithelial cells of the prostate gland. "The significant downregulation of MT1G in prostate cancer tissues, associated with poor prognosis, and its role in regulating the tumor microenvironment and immune response highlight its utility not only as a prognostic marker but also as a potential therapeutic target." (PMID 39063592, 2024). "MT1G, MSMB, SLC22A3, COMP and KRT15 have also been associated with aggressive and/or poor clinical outcome in prostate cancer." (PMID 36661662, 2022). "The ability of MT1G to modulate immune infiltration and enhance the effectiveness of immune checkpoint inhibitors could lead to novel treatment strategies in prostate cancer, particularly for patients resistant to conventional therapies." (PMID 39063592, 2024). "MT1G promotes methylation and tumor aggressiveness in prostate cancers and could serve as a marker for locally advanced disease." (PMID 33240582, 2020).
lung carcinoma (5 papers, 2016 to 2024). "Our findings revealed that EVs derived from high-metastatic lung cancer cells packaged miR-1290 that directly targets MT1G, leading to activation of AKT signaling in NFs and inducing NFs conversion to CAFs." (PMID 38825680, 2024). "A study in lung cancer showed that Metallothionein 1G (MT1G), as a target for miR-1290, have critical roles in regulating tumor growth and metastasis." (PMID 38825680, 2024). "However, only one group contended that the expression of MT1G was lower in lung cancer tissues than in peri-cancer tissues." (PMID 35354498, 2022). "Collectively, these results suggest that EVs-packaged miR-1290 promoted the activation of NFs to CAFs by targeting MT1G/AKT, and accelerated the metastatic homing of lung cancer cells." (PMID 38825680, 2024). "Consistent with this study, multidrug resistant lung cancer cells showed downregulation of MT1G expression 30 and overexpression of MT1G sensitizes colorectal cancer cells to the chemotherapeutic agents oxaliplatin and 5-fluorouracil 31, suggesting that MT1G may contribute to chemosensitivity." (PMID 33537082, 2021). "Hence, the upregulation of MT1B, MT1F, MT1G, and MT1H in HPAEpiCs after exposure to PHMG may be involved in the development of lung cancer." (PMID 34564354, 2021). "A few of the top target genes, such as MT1G and GLIPR1 were, in fact, common targets of both miR-1246 and miR-1290, thus suggesting that they may play an important role in mediating the function of lung cancer cells." (PMID 27325363, 2016).
melanoma (5 papers, 2017 to 2025). A malignant, usually aggressive tumor composed of atypical, neoplastic melanocytes. "Promoters of COL1A2, HSPB6, NPM2, MT1G or DDIT4L were identified as hypermethylated in melanoma cells suggesting that they can be used as predictors for melanoma progression." (PMID 40427015, 2025). "According to the analysis of human melanoma scRNA-seq, myeloid cells associated with responders showed a relatively high expression of PLTP, APOC1, APOE, MT1G, and MT1H." (PMID 34966676, 2021). "The results were validated by bisulfite sequencing of COL1A2, NPM2, HSPB6, DDIT4L, and MT1G promoters, which exhibited increasing incidence with advanced melanoma stage, suggesting potential use as predictors of melanoma progression." (PMID 28396701, 2017).
papillary thyroid cancer (5 papers, 2004 to 2018). "Methylation-specific PCR (MSP) was performed to analyze promoter methylation of MT1G and its relationship with clinicopathological characteristics of papillary thyroid cancer (PTC) patients." (PMID 24098937, 2013).
Clear Cell Renal Cell Carcinoma (4 papers, 2022 to 2024). "Given the significance of histone modifications in ccRCC development and the success of small molecule histone regulatory agents as therapeutic drugs, MT1G holds promise as a potential targeted drug for renal clear cell cancer." (PMID 38906969, 2024).
colorectal cancer (4 papers, 2016 to 2024). A primary or metastatic malignant neoplasm that affects the colon or rectum. "Cannabidiol was able to exert a therapeutic effect on colorectal cancer, and overexpression of MT1G and MT2A increased the number of dead cells and synergistically enhanced the anticancer effect of cannabidiol." (PMID 39061894, 2024). "When colorectal cancer occurs, the levels of MT1B, MT1F, and MT1G genes are down-regulated, and MT genes may be able to serve as effective markers for the diagnosis of the disease." (PMID 39061894, 2024).